XRCC3 (X-ray repair cross complementing 3)
Diseases named in the same sentence as XRCC3 in open-access papers (continued):
Sharing a sentence is not in itself a finding about the gene and the disease.
tumor (28 papers, 2003 to 2025). "Despite having a significant impact on tumor proliferation, there is robust binding of the G264S variant to XRCC3 slightly exceeding that of wild-type RAD51C." (PMID 37488098, 2023). "Expression abnormalities in XRCC3 are associated with tumour resistance to DNA damage-inducing antitumour agents." (PMID 37679817, 2023). "XRCC3 rs861539 was associated with tumor grade in one study, with different results for carriers of one or two T alleles." (PMID 36139526, 2022). "RAD51 polymorphisms were also associated with the occurrence of a new primary tumor, while XRCC3 polymorphisms were associated with tumor differentiation grade." (PMID 36139526, 2022). "High XRCC3 expression was associated with large tumor size and positive PR and HER2 status, while high RAD51 expression was associated with axillary lymph node metastasis and positive PR and HER2 status." (PMID 23977219, 2013). "Finally, in 2 cisplatin sensitive tumours we identify mutations in XRCC3 and ORC1 genes that are functionally validated in vitro." (PMID 37029129, 2023). "XRCC1, XRCC3, ERCC1, and ERCC2 encode proteins crucial for the repair of DNA damage induced by ionizing radiation, directly affecting tumor cell radiosensitivity." (PMID 41463244, 2025). "RAD51 paralogs, including RAD51B, RAD51C, RAD51D, XRCC2 and XRCC3, have emerged as essential tumour suppressors, forming two subcomplexes, BCDX2 and CX3." (PMID 39268578, 2024). "XRCC3 induces cisplatin resistance in tumour cells by activating Rad51-related recombination repair and S-phase monitor activation and by reducing apoptosis." (PMID 37679817, 2023). "In 3 PDX models from the responder group without BRCA1/2 mutations or BRCA1 promoter methylation, we identified mutations in the DDR genes XRCC3 (HBCx-14), TONSL (HBCx-33) and ORC1 (T302), that were present also in the matched patients’ primary tumours." (PMID 37029129, 2023). "In HBCx-14 primary and PDX tumours, we found a fusion transcript pointing towards the presence of a genomic deletion on chromosome 14 that encompasses the DNA damage repair gene XRCC3." (PMID 37029129, 2023). "Carriers of XRCC3 rs1799794 GG genotype were less likely to have grade 3 tumor compared to carriers of wild-type AA genotype (OR = 0.05, 95% CI = 0.01–0.44, p = 0.007)." (PMID 36139526, 2022). "Carriers of XRCC3 rs1799794 GG genotype were less likely to have higher tumor differentiation grade (OR = 0.05, 95% CI = 0.01–0.44, p = 0.007)." (PMID 36139526, 2022). "Individually, RAD51B displayed over 80% sensitivity and specificity, whereas XRCC3 correctly identified 43.4% of the tumor samples with 94.7% specificity." (PMID 32295201, 2020). "Five HR cofactors – the RAD51 paralogs RAD51B, RAD51C, RAD51D, XRCC2 and XRCC3 – recently emerged as crucial tumor suppressors." (PMID 32669601, 2020). "When considering the histological type of tumor, the most remarkable association was observed in the DSBR gene XRCC3, with the A allele of rs861528 being associated with a higher risk of diffuse GC (dominant model, OR: 2.11; 95% CI: 1.43–3.12)." (PMID 28415781, 2017). "Significant differences of XRCC3 expression were found between the classifications of subgroups of tumor size (P = 0.036), PR status (P = 0.031), and HER2 status (P = 0.034)." (PMID 23977219, 2013). "After 12 weeks, 4/7 mice injected with XRCC3 OE showed tumours compared to 1/8 mice injected with MOCK cells." (PMID 21283680, 2011). "In an attempt to support the in vitro results we assessed the effect of XRCC3 over-expression on the growth of MCF-7 tumour xenografts in SCID mice under suboptimal conditions (i.e. in the absence of oestradiol treatment)." (PMID 21283680, 2011). "Mice injected with XRCC3 over-expressing cells developed tumours with volumes ranging from 1 to 8 mm3 at 4 weeks post injection." (PMID 21283680, 2011).
tumor (continued). "Our results show that XRCC3 favours the growth of MCF-7 xenografts since the growth rate of tumours was roughly five times higher for XRCC3 over-expressing cells when compared to the control type (i.e. 57% vs. 12% respectively)." (PMID 21283680, 2011). "When considering the histological type of tumor, the most remarkable associations were observed in the DSBR gene XRCC3 (X-ray repair cross complementing 3), with the rs861528G>A and rs861531G>T intronic variants being associated with a higher risk of diffuse GC." (PMID 28415781, 2017). "Interestingly, similar to previous reports, the tumours showed not only nuclear but also cytoplasmic XRCC3 staining in both kinds of xenograft derived tissues." (PMID 21283680, 2011). "Our results indicate that over-expression of the XRCC3 gene is also associated with an invasive behaviour in vitro and the promotion of tumour formation in vivo, these features were independent of RAD51 and the proliferation rate of the cells." (PMID 21283680, 2011). "The tumour incidence was highly increased (P = 0.028) in mice injected with XRCC3 OE cells." (PMID 21283680, 2011). "XRCC3 expression was four-fold higher in the XRCC3 OE cell tumours." (PMID 21283680, 2011). "In contrast only 14% of MOCK tumour cells showed high levels of nuclear XRCC3 (P = 0.029)." (PMID 21283680, 2011). "Furthermore, 61% of XRCC3 OE tumour cells showed high nucleus staining compared with 14% of MOCK tumour cells." (PMID 21283680, 2011). "Importantly, immnocytochemical analysis using a specific XRCC3 antibody confirmed the over-expression of the protein in the xenograft tumour tissues." (PMID 21283680, 2011). "In addition, the xenograft analysis showed rapid tumour formation on those mice injected with XRCC3 OE cells." (PMID 21283680, 2011). "Allele XRCC3-241Met (OR 0.85, 95%CI 0.72–0.99, p < 0.045), XRCC2-41657 T (OR 1.67, 95% CI 1.42–1.96, p < .0001), BRCA1-356R (OR 1.61; % CI 1.37–1.90, p < .0001) and RAD51–135C (OR 5.16; 95% CI 4.29–6.20, p < .0001) strongly correlated with the neoplastic disease." (PMID 30712190, 2019). "The specific HRR mutations identified in the 21 tumour samples were: BRIP1 (n = 5), CDK12 (n = 3), RAD54L (n = 2), RAD51B (n = 2), RAD54L rearr (n = 1), ATM rearr (n = 1), FANCA rearr (n = 1), FANCD2 (n = 1), FANCL rearr (n = 1), FANCL (n = 1), RAD51C (n = 1), RAD52 del (n = 1), XRCC3 rearr (n = 1)." (PMID 30353044, 2018). "This occurred for an XRCC3 exon 7 CT heterozygote where the C allele was absent in the tumour." (PMID 12865926, 2003). "In this regard, the main targeting components of DNA repair machinery such as RAD51, XRCC3, RPA‐1 in HR and XRCC4, KU70, KU80 in NHEJ can open a new window for treatment of the EC by sensitizing tumor cells to radiotherapy." (PMID 36147024, 2022). "Conclusively, XRCC3, CUL4A, and CSK1E methylation highly correlated with tumor purity (Figure 4SC‐F)." (PMID 32991787, 2020). "Variables that were selected for multivariate analysis included XRCC3, RAD51, HER2, ER, PR, age at diagnosis, histology grade, tumor size, and axillary lymph node metastasis." (PMID 23977219, 2013). "Five of the seven combinations identified from the conserved tumor suppressor XRCC3 network resulted in negative effects on tumor cell clonal survival when XRCC3 is also knocked down." (PMID 31640753, 2019). "Furthermore, RAD51B and XRCC3 promoter levels were higher in tumor tissues compared to normal breast or lymph node, although with statistical significance for XRCC3, only." (PMID 32295201, 2020). "Furthermore, XRCC3 promoter methylation levels were lower in normal adjacent tissue comparing to tumor tissue (p = 0.002), whereas RAD51B promoter methylation levels were higher in tumor samples, although not reaching statistical significance (p = 0.968)." (PMID 32295201, 2020).
XRCC3 also shares sentences with these, for which no sentence is quoted: acute myeloid leukemia (2 papers); adenoma (1); anemia (1); arterial hypertension (1); Brain tumors (1); Chronic Myeloid Leukemia (1); cutaneous melanoma (1); diabetes mellitus (1); endometrial tumors (1); Fanconi anemia complementation group A (1); female reproductive diseases (1); gastrointestinal neoplasms (1); genetic disorder (1); Huntington disease (1); Liver Abnormality (1); lymphoma (1); meningioma (1); migraine (1); neuropathy (1); oesophageal cancer (1); oral mucositis (1); osteoporosis (1); pancreatic adenocarcinoma (1); pancreatitis (1); Parkinson disease 7 (1); prolactinoma (1); prostate tumors (1); radiation pneumonitis (1); reproductive diseases (1); skin toxicity (1).
A further 4 diseases each share a sentence with XRCC3 in 1 paper.